NUSAP1 (nucleolar and spindle associated protein 1)
Diseases named in the same sentence as NUSAP1 in open-access papers (continued):
Sharing a sentence is not in itself a finding about the gene and the disease.
cancer (57 papers, 2011 to 2025). A tumor composed of atypical neoplastic, often pleomorphic cells that invade other tissues. "GSEA and GSVA results highlighted the association between NUSAP1 and lipid metabolism, a process pivotal in cancer cell tumorigenesis, disease progression, immune cell recruitment, and modulation of the immune microenvironment response." (PMID 39781524, 2025). "Disruptions in the proper protein level of NUSAP1 can lead to chromosome misalignment and unequal chromosome separation, resulting in genetic instability, a hallmark of cancer." (PMID 37781040, 2023). "In the analysis of prognostic predictive power using OS, DSS, DFI, and PFI, we observed a significant association between NUSAP1 expression level and prognosis in 26 cancer types." (PMID 37781040, 2023). "Aberrant proliferation with cell cycle dysregulation is a common feature of cancer cells, leading to several studies associating NUSAP1 with various malignant features of human tumors 7-13." (PMID 37781040, 2023). "To gain a better understanding of the association between NUSAP1 expression and clinical features in these cancers, we downloaded and analyzed clinical phenotype data of TCGA." (PMID 37781040, 2023). "A recent pan-cancer analysis confirms that increased levels of DNA structural alterations are associated with advanced cancer stages in many cancers, including those where increased NUSAP1 expression levels are associated with adverse outcomes." (PMID 37047232, 2023). "Given its role in mitosis, a logical assumption would be that overexpression of NUSAP1 is merely a surrogate for more highly mitotic cancers, and high proliferation rates are associated with poor outcomes in most malignancies." (PMID 37047232, 2023). "Nucleolar and spindle-associated protein 1 (NUSAP1) was shown to be involved in cell cycle regulation in cancer." (PMID 35739489, 2022). "Although NUSAP1 is characterized as an oncogenic driver in several cancers, the underlying mechanisms remain elusive." (PMID 33489890, 2020). "NUSAP1, which is a microtubule-associated protein involved in mitosis, plays essential roles in diverse biological processes, especially in cancer biology." (PMID 32317623, 2020). "Nucleolar and spindle associated protein 1 (NUSAP1) has been implicated in the development, progression, and metastasis in several types of cancer." (PMID 30678687, 2019). "Surprisingly, little work has examined the role of NUSAP1 in cancer, despite several reports documenting that overexpression of NUSAP1 is associated with significantly worse outcome." (PMID 28404898, 2017). "Nucleolar and spindle-associated protein 1 (NUSAP1) is critical for cancer progression." (PMID 41178464, 2025). "Altered NUSAP1 expression has been hypothesized to be associated with cancer cell growth and proliferation." (PMID 40535133, 2025). "Nucleolar and spindle-associated protein 1 (NUSAP1), a microtubule-associated protein, has been recently identified to exhibit aberrant expression patterns that correlate with malignant tumorigenesis and progression across various cancer types." (PMID 39430250, 2024). "NUSAP1 is linked to the development of different forms of cancers." (PMID 38795225, 2024). "Furthermore, we assessed the association between NUSAP1 expression level and clinical features in these cancer types." (PMID 37781040, 2023). "To better understand the mechanisms underlying the association of NUSAP1 overexpression and cancer aggressiveness, we used AP–MS to identify novel interactions between NUSAP1 and several proteins with described functions in R-loop biology and DDR, including DHX9, ILF2, HNRPC, FUS, and RBMX." (PMID 37047232, 2023). "Increased NUSAP1 expression has been associated with adverse clinical outcomes in many cancers." (PMID 37047232, 2023).
cancer (continued). "Relatedly higher mRNA levels of NUSAP1 were found in testis and numerous organs, including esophagus, adrenal gland, skin, ovary, colon, lung, stomach, liver, kidney, cervix, breast, and prostate, which are known to be susceptible to cancer development." (PMID 37781040, 2023). "However, the underlying molecular mechanisms of elevated levels of NUSAP1 in cancer formation would require further basic and clinical research for exploration and understanding." (PMID 37781040, 2023). "NUSAP1 (nucleolar and spindle-associated protein 1) playing a critical role in cell division and being a useful prognostic marker, has been implicated in various types of cancer, including BC." (PMID 37370847, 2023). "Consequently, the aberrant expression of NuSAP1 has been associated with defective embryogenesis and cancer." (PMID 26485712, 2015). "The results revealed that both four different types of NUSAP1 gene mutations, including deep deletion, arm-level deletion, arm-level gain, and high amplification, could decrease the infiltration of six immune cells in most cancer types." (PMID 37781040, 2023). "By increasing nuclear B-catenin levels, NUSAP1 initiates the activation of the Wnt/B-catenin signaling pathway, which consequently supports the metastasis of cancer cells." (PMID 40535133, 2025). "Further studies have demonstrated that ANKRD22 indirectly activates the Wnt/B-catenin signaling pathway by modulating the expression of NUSAP1, consequently facilitating the malignant progression of cancer cells." (PMID 40535133, 2025). "Accumulating evidence demonstrates that NUSAP1 promotes cancer cell proliferation and invasion by stimulating both Wnt/B-catenin signaling and EMT pathways." (PMID 40535133, 2025). "Prior research has established a correlation between elevated NUSAP1 expression and adverse outcomes in various cancers, including breast, lung, and prostate." (PMID 39975552, 2025). "Knockdown of NUSAP1 to silence its expression effectively inhibits cancer cells’ proliferation, invasion, migration, and EMT." (PMID 40535133, 2025). "NUSAP1 promoted cancer cell proliferation, migration and invasion, drives the epithelial-mesenchymal transition and reduces AMPK phosphorylation." (PMID 38229038, 2024). "To further investigate the cancer-promoting mechanism of NUSAP1, we focused on identifying additional therapeutic targets by examining both upstream and downstream regulators of NUSAP1." (PMID 38441732, 2024). "In our study, we found that NUSAP1 promoted the proliferation, epithelial mesenchymal transition, migration and invasion of cancer cells in vitro." (PMID 38229038, 2024). "Nevertheless, our findings provide compelling evidence that the anti-cancer effect of entinostat is, at least partially, mediated through the inhibition of NUSAP1 expression." (PMID 39430250, 2024). "NUSAP1 knockout decreased the expression of surface markers of cancer stem cells (CSCs), and NUSAP1 was highly expressed in self-renewing CSCs." (PMID 38441732, 2024). "Further studies on the downstream signaling pathways of NUSAP1 will help to elucidate the specific mechanisms by which NUSAP1 promotes cancer and identify additional therapeutic targets for cancer treatment." (PMID 38441732, 2024). "Firstly, we assessed the mRNA expression of NUSAP1 across pan-cancer by analyzing data from the TCGA and GTEx database." (PMID 39430250, 2024). "Our results showed that, in comparison to normal samples, the expression levels of NUSAP1 mRNA were significantly elevated in most human cancer tissues, including LUAD." (PMID 39430250, 2024). "The HPA database also confirmed similar expression patterns of NUSAP1 protein in other cancer types." (PMID 37781040, 2023). "In recent years, NUSAP1 has been considered as an important regulator in the occurrence and development of malignant tumors." (PMID 36982952, 2023).
cancer (continued). "Kaplan–Meier analysis demonstrated that cancers with high NUSAP1 and ILF2 mRNA levels had a significantly worse disease-free survival rate." (PMID 37047232, 2023). "Prognostic analysis based on curated survival data from the TCGA database indicates that NUSAP1 expression levels can predict clinical outcomes for 26 cancer types." (PMID 37781040, 2023). "In this study, we utilize various public databases and our collected cancer samples to investigate the differential expression levels of NUSAP1 in cancer and normal tissues." (PMID 37781040, 2023). "High NUSAP1 expression was positively correlated with the release of cancer cell antigen (Step 1), recruitment of Th1 cell (Step 4) and recognition of cancer cell by T cells (Step 6)." (PMID 37781040, 2023). "These future endeavors will enhance our understanding of NUSAP1's role and its potential as a therapeutic target in cancer treatment." (PMID 37781040, 2023). "This analysis examined differentially expressed genes between NUSAP1-high and -low patients in each cancer type." (PMID 37781040, 2023). "Considering the significance of PD-L1, TMB and MSI as important biomarkers for immunotherapy, the correlation between TMB/MSI and NUSAP1 expression was also assessed across multiple cancer types." (PMID 37781040, 2023). "Our current findings further extend our understanding of NUSAP1 from its mechanistic role in regulating genetic integrity to its predictive power for prognosis and immunotherapy response in pan-cancer." (PMID 37781040, 2023). "NUSAP1 is involved in microtubule organization and binding, and its promoting effect on cancer malignant phenotype has been explored in multiple studies." (PMID 37752167, 2023). "In conclusion, our study reveals that NUSAP1 exhibits significant upregulation in most cancer tissues compared to normal tissues, with predominant expression in malignant and immune cells, particularly proliferative T cells." (PMID 37781040, 2023). "To investigate the change in mRNA levels, we examined the differential expression of NUSAP1 transcripts in normal and cancer tissues." (PMID 37781040, 2023). "The analyzed results uncovered significantly higher NUSAP1 expression in almost all cancer tissues compared to normal tissues, except for ACC, KICH, and PCPG." (PMID 37781040, 2023). "In conclusion, these results strongly suggest that elevated levels of NUSAP1 are tightly associated with increased proliferation, EMT, and immunosuppression in human cancers." (PMID 37781040, 2023). "The resulting heatmap revealed significant enrichment of cell proliferation-related signaling pathways, including MYC, mTORC1, Mitotic spindle, G2M, and E2F pathways, in the NUSAP1-high patients across almost all cancer types." (PMID 37781040, 2023). "To compare the mRNA levels of NUSAP1 between cancer and normal tissues, we downloaded expression data from the TCGA and GTEx databases." (PMID 37781040, 2023). "Taken together, our findings highlight the important roles of NUSAP1 in tumorigenesis and cancer progression." (PMID 37781040, 2023). "To predict the potential signaling regulation in cancers, we examined the phosphorylation sites of NUSAP1 using the CPTAC database." (PMID 37781040, 2023). "In recent years, NUSAP1 has been reported to be a potential biomarker and therapeutic target in human cancers." (PMID 36982952, 2023). "The mechanisms by which NUSAP1 contributes to cancer progression, metastases, and poor outcomes are poorly understood." (PMID 37047232, 2023). "Consistently, the elevated expressions of NUSAP1 in most cancers were also validated in the GEO datasets." (PMID 37781040, 2023). "Herein, through the joint analysis of Oncomine, TCGA, and CCLE databases, we found that NUSAP1 is highly expressed in multiple malignant tumors, and its protein level is correlated with FIGO stage." (PMID 35739489, 2022).
cancer (continued). "In this study, we followed up cancer patients for more than 5 years to explore the prognostic value of NUSAP1." (PMID 35739489, 2022). "Specifically, NUSAP1 exerts cancer-promoting functions in GC cells, and these effects are partially reversed by YAP1 depletion." (PMID 33489890, 2020). "NUSAP1 has been demonstrated to regulate several cancer-promoting genes and pathways, including BRCA1, Wnt/β-catenin, mTORC1, Hedgehog, etc." (PMID 33489890, 2020). "More interestingly, we find that the cancer-promoting effects of NUSAP1 on GC cell growth, migration, and invasion are mainly mediated by YAP1." (PMID 33489890, 2020). "High expression of NUSAP1 promoted metastasis by enhancing cancer stem cell (CSC) traits and epithelial-mesenchyme transition (EMT) progression, while silencing of NUSAP1 reduced CSC traits and EMT progression." (PMID 30678687, 2019). "GSEA plot showing that NUSAP1 expression positively correlated with metastasis and cancer stem cell in GSE 6919 datasets." (PMID 30678687, 2019). "The breadth of studies implicating NUSAP1 suggests it plays an important functional role in cancer progression." (PMID 28404898, 2017). "NUSAP1 overexpression is also prognostic in other cancer types, including melanoma, breast cancer, glioblastoma, hepatocellular carcinoma, and meningioma." (PMID 28404898, 2017). "In general, FAM101B and NUSAP1 expression correlate in the cell lines and cancers tested; however, it should be noted that medium to high levels of NUSAP1 expression are found in additional and most cell lines and cancers tested." (PMID 28404898, 2017). "To investigate mRNA expression of NUSAP1 identified as a cancer-related gene by our previous microarray data, we performed qRT-PCR analysis using 9 OSCC-derived cell lines and HNOKs." (PMID 26554377, 2015). "Consequently, dysregulated NUSAP1 expression levels frequently result in aberrant cell proliferation, leading to embryonic developmental abnormalities and various cancers." (PMID 40535133, 2025). "Therefore, abnormal expression levels of NUSAP1 often lead to abnormal cell proliferation, a characteristic that aligns with the mechanism of cancer occurrence." (PMID 40535133, 2025). "Lactate-driven nuclear localization of NUSAP1 is critical for its function, as nuclear NUSAP1 recruits the JUNB-FRA1-FRA2 transcriptional complex to the DESMIN promoter, activating DESMIN transcription and promoting cancer-associated fibroblast (CAF) activation." (PMID 40393971, 2025). "Extensive evidence suggests NUSAP1's involvement in the onset and progression of various cancers." (PMID 39781524, 2025). "In contrast, silencing NUSAP1 markedly decreases the expression of DNMT1 at both mRNA and protein levels, indicating that NUSAP1 may affect the malignant behavior of cancer cells through modulation of DNMT1 expression." (PMID 40535133, 2025). "Dysregulation of NUSAP1’s ability to maintain stable cell proliferation frequently results in various adverse consequences, including early embryonic lethality and the development and progression of various cancers." (PMID 40535133, 2025). "These researches indicate that NUSAP1 may play a decisive function in the occurrence and development of EC by modulating cancer cell proliferation and apoptosis." (PMID 40535133, 2025). "Recently, abnormal NUSAP1 expression has gained significant attention in various cancers." (PMID 39975552, 2025).
cancer (continued). "Moreover, NUSAP1 is crucial in determining the sensitivity and resistance to chemotherapy drugs; reducing its expression can enhance the sensitivity of cancer cells to chemotherapeutic agents." (PMID 40535133, 2025). "Given the central role of NUSAP1 in pro-cancer signaling pathways, targeting NUSAP1 for inhibition may enable coordinated blockage of multiple pathways, thereby establishing it as a highly promising therapeutic target for cancer treatment." (PMID 40535133, 2025). "Recent studies have demonstrated that NUSAP1 is highly expressed in various malignant tumors of the digestive system and plays a pivotal role in the initiation, progression, treatment, and prognosis of these tumors by regulating mitosis and key signaling pathways." (PMID 40535133, 2025). "Under hypoxic conditions, NUSAP1 expression in PC cells increases more than tenfold, suggesting that NUSAP1 may facilitate cancer cell proliferation and metastasis under hypoxic stress." (PMID 40535133, 2025). "We speculate that NUSAP1 may participate in discrepant functional process of mitosis in different types of cancer, resulting in opposing effects." (PMID 39430250, 2024). "Consequently, NUSAP1 has a pivotal role in mitosis and contributes to the development and prognosis of various cancers." (PMID 38441732, 2024). "Additionally, we characterize the potential function of NUSAP1 and its influence on immune cell infiltration in pan-cancer." (PMID 37781040, 2023). "This correlation may explain why patients with high NUSAP1 levels in these cancer types are prone to lymph node and distant metastasis, as well as recurrence." (PMID 37781040, 2023). "Overall, our study highlights the potential of NUSAP1 expression as a novel biomarker for predicting prognosis and immuno-therapeutic efficacy across different human cancers and suggests its potential for developing novel antitumor drugs or improving immunotherapy." (PMID 37781040, 2023). "R-loops have been implicated in promoting DNA damage and genomic instability, suggesting that elevated levels of NUSAP1 could drive cancer aggressiveness by increasing genomic instability." (PMID 37047232, 2023). "In this study, we conducted a comprehensive pan-cancer analysis and uncovered that NUSAP1, an important regulator of mitosis, could serve as a robust predictive biomarker for the prognosis and immunotherapy response of human cancers." (PMID 37781040, 2023). "Given the results of our previous analysis, which demonstrated the regulatory role of NUSAP1 expression levels in immune responses and immune cell infiltration in various human cancers, we proceeded to examine the predictive effect of NUSAP1 on cancer immunotherapy." (PMID 37781040, 2023). "While these downstream pathways could contribute to cancer aggressiveness, we speculated that NUSAP1 protein has additional means of driving progression through its interactions with protein-binding partners." (PMID 37047232, 2023). "In addition to NUSAP1 expression levels, we also observed the effect of NUSAP1 mutations on the infiltration of six immune cells (B, CD8+T, CD4+T, macrophages, neutrophils, and dendritic cells) into the TME of 31 cancer types." (PMID 37781040, 2023). "Notably, the expression level of NUSAP1 holds substantial promise as a valuable biomarker for predicting prognosis and assessing the effectiveness of immunotherapy in human cancers." (PMID 37781040, 2023). "In other words, the increased DNA damage arising from R-loops in cancers with high NUSAP1 expression could represent a therapeutic vulnerability that could be exploited by blocking DNA repair using PARP inhibition." (PMID 37047232, 2023). "It has been reported that NUSAP1 is abnormally expressed in various cancers." (PMID 35483343, 2022). "We initially evaluated NUSAP1 expression in multiple cancers through the Oncomine database." (PMID 35739489, 2022).